PYCARD (PYD and CARD domain containing)
Diseases named in the same sentence as PYCARD in open-access papers (continued):
Sharing a sentence is not in itself a finding about the gene and the disease.
tumor (continued). "Furthermore, we found that the methylation status of tested genes in tumor tissue could be used as a potential prognostic biomarker in patients with early-stage NSCLC because hypomethylation of specific CpG sites in ASC/TMS1/PYCARD gene was associated with reduced overall survival." (PMID 33637109, 2021). "PYCARD expression is found in tumor cells, tumor-associated macrophages, normal epithelial cells, and non-tumor adjacent tissues." (PMID 33649342, 2021). "The significantly regulated genes identified in both KYSE150 and KYSE410 cells were found to be involved in cell adhesion (PCDH family genes, CLDN1, CNTN1), cell apoptosis (MAPK10/JNK3, PYCARD), tumor suppression (TUSC3, SAMD9L) and immunity regulation (IFNL3)." (PMID 32089740, 2020). "In addition, increased LAG3 and CTLA4 expressions in the high-PYCARD group suggested the presence of a suppressive immune microenvironment and exhaustions of active immune cells, which may promote immune escape and tumor progression." (PMID 36291776, 2022). "Therefore, in the context of cancer development and progression, PYCARD may exert opposing functions, either tumor-suppressing by inducing apoptosis or tumor-promoting by secretion of inflammatory cytokines within the tumor microenvironment." (PMID 33649342, 2021). "High NLRP3, PYCARD and TLR4 expression was found in 31.8% (106/333), 38.6% (129/334) and 35.6% (115/323) of the tumor samples, respectively." (PMID 34540671, 2021). "Several genes encoding core inflammasome components were all significantly expressed at higher levels in ACP tumours compared with control tissues, including NLRP1 (6.4-fold), NLRP3 (4.8-fold), NLRC4 (4.8-fold), CASP1 (5-fold) and PYCARD (4-fold) [Suppl." (PMID 29541918, 2018). "All of these genes are known to be involved in different aspects of breast carcinogenesis, which includes tumor suppression, HIC1, CDH1, CDH13, CDKN2, DNA repair, MGMT, apoptosis, PYCARD, TNFRSF10C, and cell cycle regulation, CCNA1." (PMID 25403427, 2014). "Furthermore, not all the transcripts associated with the inflammasome complex were enriched in the tumor, such as IL18, AIM2, PYCARD, and GSDMD." (PMID 36439171, 2022). "Our recent data demonstrated a higher NLRP3 and PYCARD expression in the tumor compartment with respect to the non-tumor areas in a BC cohort." (PMID 35745570, 2022). "Because tumor-specific PYCARD methylation was not frequent in Gleason score 6 specimens, analyses of PYCARD methylation in HGPIN should add further valuable information to clarify the role of PYCARD methylation in prostatic tumorigenesis." (PMID 33628338, 2021). "In our BC cohort, NLRP3 and PYCARD expression was higher in the tumor samples than in the non-cancerous counterparts, thus confirming inflammasome involvement in establishing a tumor-associated microenvironment to support cancer progression." (PMID 34540671, 2021). "Therefore, we first analyzed mRNA expression of Caspase-1, PYCARD, and NLRP3 in paired normal and tumor tissues collected from CRC patients by qPCR experiments." (PMID 33102234, 2020). "The results demonstrated that PYCARD could not serve as an indicator to evaluate whether the tumor metastasized or not currently." (PMID 36291776, 2022). "For example, PYCARD was downregulated in the C5 (immunologically quiet) group when compared with other immune subtypes in KIRC, which indicated that PYCARD might play an important role in taking part in the crosstalk of the immune infiltrating cells within the tumor microenvironment (TME)." (PMID 36291776, 2022). "While PYCARD (cg11970458), but not SLC12A9 (cg04742719), exhibits a role in PCa, the observed tumour versus normal hypermethylation of these particular CpGs appears to be African-specific." (PMID 41057544, 2025).
cancer (29 papers, 2008 to 2025). A tumor composed of atypical neoplastic, often pleomorphic cells that invade other tissues. "The results showed that PYCARD expression varied in several cancers and was associated with prognosis, immune-related genes, published biomarkers, and immunotherapy response." (PMID 36291776, 2022). "Pan-cancer analysis of PYCARD suggested that the function of PYCARD differed in different types of cancer due to distinct mutation backgrounds." (PMID 36291776, 2022). "The dual role of the inflammasome adaptor PYCARD is identified in cancer cells, and therefore, PYCARD can be associated with lower cancer risks." (PMID 34867395, 2021). "Low expression of PYCARD is detected in various types of cancers, including BC, and associated with tumorigenesis." (PMID 33297339, 2020). "We found that PANoptosis genes were aberrantly expressed in most cancer types, which was consistent with the validation of PYCARD expression." (PMID 36890219, 2023). "Based on the expression and survival analysis of PANoptosis genes in pan-cancer, we further validated the expression level of PYCARD in KIRC, GBM, and PAAD." (PMID 36890219, 2023). "In conclusion, PYCARD demonstrated strong correlations with prognosis, immune response, and disease progression in pan-cancer analysis." (PMID 36291776, 2022). "In our study, we found that PYCARD expression varied among human cancers and correlated to prognosis." (PMID 36291776, 2022). "We found that ICP genes had significantly close correlations with PYCARD expression in almost pan-cancer." (PMID 36291776, 2022). "Since PYCARD was differentially expressed in cancer and normal tissue, we performed differential gene analysis between high and low PYCARD groups." (PMID 36291776, 2022). "PYCARD is also proposed to be involved in lymphocyte activation and was found to be upregulated in cancer patients." (PMID 33580122, 2021). "In our study, however, the great majority of cancer specimens (90%, 45/50) showed hypermethylation of the PYCARD promoter." (PMID 33628338, 2021). "We then examined the effect of PYCARD on ESCC cell proliferation and migration and identified 169 MRGs at the single-cell and transcriptome levels, as well as the high-risk groups associated with cancer-related pathways." (PMID 39344350, 2024). "We observed that NLRP7 (n = 8), AIM2 (n = 10), CASP8 (n = 6), GSDMA (n = 5), GSDMB (n = 8), and GSDMC (n = 12) mainly showed hypomethylation in most cancers, and PLCG1 (n = 11), NLRP6 (n = 13), ELANE (n = 11), CASP6 (n = 5), NLRC4 (n = 12), and PYCARD (n = 8) showed hypermethylation in most cancers." (PMID 35246158, 2022). "Previous studies found that PYCARD had various functions in different human cancers." (PMID 36291776, 2022). "In our study, PYCARD expression and prognostic value were examined in the pan-cancer analysis." (PMID 36291776, 2022). "The overall genetic alterations of PYCARD accounted for 1.1% of pan-cancer patients." (PMID 36291776, 2022). "The objective of our study was to explore PYCARD expression and prognostic value in human cancers." (PMID 36291776, 2022). "However, due to the intricate cancer-specific genetic backgrounds, the significance of PYCARD in tumorigenesis requires systematic reassessments." (PMID 36291776, 2022). "Therefore, up-regulation of PYCARD in PDT treated Caco-2 cells clearly demonstrates the ability of ZnPcSmix to induce cell death in cancer cells." (PMID 31269724, 2019). "However, the function of PYCARD in human cancers remains unclear." (PMID 36291776, 2022). "Significantly upregulated PRGs included PYCARD in 12 cancers; GSDMB in 10 cancers; IL18 in 9 cancers; GSDMD, CASP8, GZMB, and GPX4 in 8 cancers; AIM2 and CASP6 in 7 cancers; GZMA in 6 cancers; GSDME, CASP4 and DHX9 in 5 cancers; GSDMA and GSDMC in 4 cancers." (PMID 36605187, 2022). "However, the function of PYCARD remains unclear in human cancers." (PMID 36291776, 2022).
cancer (continued). "GSDMC, NLRP7, CASP5, PYCARD, IL18, IL1B and GSDMA were significantly upregulated in 22, 18, 18, 18, 18, 16 and 17 types of cancers, respectively." (PMID 35246158, 2022). "A number of cancer-related genes are located in these two RARs: NUPR1, MVP, MAPK3, FUS, and PYCARD are located in RAR-G12 while ERBB2, GRB7, and PPP1R1B are located in RAR-G13." (PMID 22938721, 2012). "According to PubMeth, DAPK1, PYCARD, RB1, and TP73 are methylated in at least half of our fourteen cancer models." (PMID 19402918, 2009). "From the lncRNA-mRNA pathway network, PYCARD, RIPK2, and CASP1 were found to be significantly enriched in the NOD-like receptor signaling pathway, whereas MAP2K2, LUM, RPS6, PDCD4, TWIST1, and HIF1A were significantly enriched in proteoglycans in cancers." (PMID 36619896, 2022). "It is interesting to note that PYCARD silencing did not influence apoptosis-related expression levels in cancer cell lines." (PMID 36291776, 2022). "In our proposed DMD-related lncRNA-mRNA pathway networks, PYCARD, RIPK2, and CASP1 were significantly enriched in the NOD-like receptor signaling pathway, whereas MAP2K2, LUM, RPS6, PDCD4, TWIST1, and HIF1A were significantly enriched in proteoglycans in cancers." (PMID 36619896, 2022). "To investigate further the role of promoter DNA methylation of genes aberrantly hypermethylated in cancer in hESCs, we compared the DNA methylation and expression status of four of the genes identified in the methylation arrays (MGMT and SLC5A8 from Class B-I, and PYCARD and RUNX3 from Class B-II)." (PMID 18820729, 2008).
infection (11 papers, 2010 to 2025). The state of being infected such as from the introduction of a foreign agent such as serum, vaccine, antigenic substance or organism. "Notably, inflammasome scores (based on IL1B, IL18, NLRP3, GSDMD, PYCARD) remained stable in YG CMs and IMs during infection but increased consistently in AG subsets from 4 to 6 dpi." (PMID 40794649, 2025). "In addition, the infection may also indirectly downregulate neutrophil function by downregulating functional related-genes of neutrophils, such as PYCARD and NCSTN." (PMID 35111158, 2021). "Although WT infection-specific regulation was observed only for TLR8 and IFNGR1, all four genes were expressed at higher levels (TLR8 and TLR9) or at lower levels (IFNGR1 and PYCARD) in the WT-infected dTHP1 cells than in the mock-treated or ΔrtxA1 mutant-infected dTHP-1 cells." (PMID 32817457, 2020).
bacterial infection (2 papers, 2010 to 2016). "Furthermore, a previous report showed that human PYCARD is required for TNFα and IL-6 expression upon bacterial infection." (PMID 20808838, 2010).
cardiovascular diseases (1 paper, 2024). "The study identified specific PYCARD gene variations (high T and G allele frequencies) associated with an increased risk of periodontal and cardiovascular diseases in the Iraqi population." (PMID 38813354, 2024).
Genetic Disorder (1 paper, 2012). "PYCARD was over-expressed and associated with Genetic Disorder and Imflammatory disease in HvLg vs. LvLg." (PMID 23335940, 2012).
kidney disease (1 paper, 2024). "The relatively higher expression of CASP4, CASP11, and GBPs compared to CASP1, PYCARD, and NLRP3, however, may suggest a more prominent role of non-canonical versus canonical inflammasome activation contributing to kidney disease." (PMID 38838223, 2024).
PYCARD also shares sentences with these, for which no sentence is quoted: bladder cancer (3 papers); colitis (3); Alzheimer disease (2); asthma (2); glioblastoma (2); gout (2); head and neck squamous cell carcinoma (2); leukemia (2); non-small cell lung carcinoma (2); renal cell carcinoma (2); sarcoma (2); AA amyloidosis (1); adrenocortical cancers (1); autoimmune disease (1); Brain atrophy (1); Cerebral atrophy (1); cervical squamous cell carcinoma (1); cholangiocarcinoma (1); cholesteatoma (1); colon adenocarcinoma (1); colon cancer (1); coronary heart disease (1); cystitis (1); emphysema (1); endocervical adenocarcinoma (1); epilepsy (1); esophageal carcinoma (1); gastritis (1); germinoma (1); Granuloma (1).
A further 20 diseases each share a sentence with PYCARD in 1 paper.